XRCC1 (X-ray repair cross complementing 1)
Diseases named in the same sentence as XRCC1 in open-access papers (continued):
Sharing a sentence is not in itself a finding about the gene and the disease.
colorectal tumour (1 paper, 2017). "We treated colorectal tumour HCT116 cells transiently overexpressing MPG or XRCC1 with 5-FU (2.5μM and 5μM) and with TMZ (10μM and 20μM) for 24h and 48h." (PMID 28903334, 2017).
Coronary Artery Disease (1 paper, 2016). "Summary of meta-analysis of the association between XRCC1 gene polymorphisms and coronary artery disease." (PMID 27870881, 2016).
cortical cataract (1 paper, 2023). A cataract (disease) that involves the lens cortex. "DNA damage in advanced cortical cataracts remained at 72 h post-irradiation due to the presence of 8-OHG and a DNA repair protein, XRCC1." (PMID 37773127, 2023).
diabetic nephropathy (1 paper, 2023). "Recently an association between other members of the same protein family (XRCC1 and XRCC3) and diabetic nephropathy has been suggested." (PMID 36769128, 2023).
Down syndrome (1 paper, 2012). "Further association with the Down’s syndrome, seizure episodes and ischemic insults render XRCC1 a critical player in CNS homeostasis." (PMID 23203191, 2012). "Increased XRCC1 expression might be explained by the higher levels of ROS detected in Down’s syndrome neurons." (PMID 23203191, 2012).
fibrosarcoma (1 paper, 2020). A malignant mesenchymal fibroblastic neoplasm affecting the soft tissue and bone. "To further elucidate the contribution of BER in the DDR after high-LET particle irradiation, we followed the real-time recruitment of the repair factor XRCC1 using human fibrosarcoma cells (HT1080) stably expressing EGFP-tagged XRCC1." (PMID 31996740, 2020).
follicular lymphoma (1 paper, 2015). Follicular lymphoma is a form of non-Hodgkin lymphoma characterized by a proliferation of B cells whose nodular structure of follicular architecture is preserved. "Abnormal expression of XRCC1 or HOGG1 was also found in myeloid leukemia and the majority of follicular lymphomas." (PMID 26376733, 2015).
gallstones (1 paper, 2020). Solid crystalline precipitates in the biliary tract, usually formed in the gallbladder, resulting in the condition of cholelithiasis. "In agreement with previous researches, our results also showed that gallbladder SC/ASC and AC had similar clinicopathological features such as tumor differentiated degree, tumor size, the existence of gallstone, TNM stage, and XRCC1 expression." (PMID 32426369, 2020).
gynecologic cancer (1 paper, 2021). "XRCC1 Arg399Gln, Arg194Trp, Arg280His single nucleotide polymorphisms were associated with gynecologic cancer susceptibility." (PMID 34918657, 2021). "Sensitivity analysis was performed on the relationship between XRCC1 Arg399Gln GGvs AA and susceptibility to gynecologic cancer." (PMID 34918657, 2021). "Sensitivity analysis of the relationship between XRCC1 Arg194Trp CCvs TT and susceptibility to gynecologic cancer." (PMID 34918657, 2021). "Egger test (XRCC1 and susceptibility to gynecological cancer)." (PMID 34918657, 2021). "XRCC1 genotype detection at each site is expected to be a molecular marker for gynecologic cancer screening." (PMID 34918657, 2021). "Genotype distribution of included XRCC1 Arg399Gln, Arg194Trp, Arg280His in gynecological cancer." (PMID 34918657, 2021). "In the sensitivity analysis of Arg194Trp CCvs TT in XRCC1 and susceptibility to gynecologic cancer, after 1 article was removed in turn, no significant changes were found in the effect scale of 16 articles, and the results were still within 95% CI (95% confidence interval)." (PMID 34918657, 2021).
Hepatitis (1 paper, 2014). Inflammation of the liver. "Previous data have suggested that for the combination of XRCC1 Arg194Trp and Arg280His or Arg399Gln, there is a markedly increased risk of hepatitis-related HCC." (PMID 25202399, 2014).
HIV-1 infection (1 paper, 2022). The type species of lentivirus and the etiologic agent of acquired immunodeficiency syndrome (AIDS). "We also observed that homozygous genotype CC and C allele of XRCC1 rs25487 were significantly associated with susceptibility to HIV-1 infection." (PMID 35368687, 2022). "In addition, our results showed that homozygous genotype CC, heterozygous genotype CT and allele C of XRCC1 rs1001581 were significantly associated with increased susceptibility to HIV-1 infection." (PMID 35368687, 2022). "Associations between APEX1 and XRCC1 gene polymorphisms and susceptibility to HIV-1 infection." (PMID 35368687, 2022). "Therefore, this study aims to investigate the role of functional polymorphisms of XRCC1 and APEX1 genes in the susceptibility and clinical progression of HIV-1 infection, and to provide a theoretical basis for the prevention and treatment of the disease." (PMID 35368687, 2022).
Hodgkin’s disease (1 paper, 2024). "Despite this, the association between XRCC1 Arg/Gln and XPC Lys/Lys was found to decrease the risk of developing Hodgkin’s disease (OR = 2.14; 95% CI = 1.09−4.23)." (PMID 38541232, 2024).
idiopathic pulmonary fibrosis (1 paper, 2019). Idiopathic pulmonary fibrosis (IPF) is a nonneoplastic pulmonary disease that is characterized by the formation of scar tissue within the lungs in the absence of any known cause. "For example, it has been shown that lung fibroblasts from idiopathic pulmonary fibrosis (IPF) patients is due to CK2 hyperactivation, which in turn promotes an abnormally high XRCC1 activity." (PMID 31277672, 2019).
injury (1 paper, 2023). Damage inflicted on the body as the direct or indirect result of an external force, with or without disruption of structural continuity. "Cellular expression of XRCC1 might be involved in the development of cardiorenal syndrome-induced kidney injury." (PMID 37773127, 2023).
larynx squamous cell carcinoma (1 paper, 2013). "In subgroup analysis, we observed an increased risk of XRCC1 codon 399 Arg/Gln genotype for HNSCC in Caucasians (OR = 1.20, 95% CI: 1.00–1.44) and Gln/Gln genotype for larynx squamous cell carcinoma (OR = 1.63, 95% CI: 1.10–2.40)." (PMID 24205020, 2013). "The results from this present meta-analysis suggest that XRCC1 Arg399Gln variants may contribute to HNSCC risk among Caucasians and to the risk of larynx squamous cell carcinoma." (PMID 24205020, 2013).
Lymphatic Metastasis (1 paper, 2014). Transfer of a neoplasm from its primary site to lymph nodes or to distant parts of the body by way of the lymphatic system. "The XRCC1 Arg280His polymorphism enhanced susceptibility of DTC in Caucasians but protect against DTC in Asians, whereas a homozygous XRCC1 Arg194Trp polymorphic genotype may increase the risk of PTC and lymphatic metastasis." (PMID 24723911, 2014).
male infertility (1 paper, 2010). The inability of the male to effect fertilization of an ovum after a specified period of unprotected intercourse. "Similar to our previous studies, we observed a joint effect between XRCC1 Arg399Gln and PAHs exposure on the susceptibility to sperm DNA fragmentation and male infertility." (PMID 20957144, 2010).
meningioma (1 paper, 2022). A generally slow growing tumor attached to the dura mater. "Interestingly, specific polymorphisms affecting genes such as caspase 8, NF2, XRCC1, and BRIP1 are related to increased risk for meningioma rise." (PMID 35891812, 2022).
myeloproliferative diseases (1 paper, 2015). "Also, a decrease in XRCC1, and thus defective BER, seems to be a contributing factor to the development of myeodysplastic and myeloproliferative diseases." (PMID 25800737, 2015).
oesophageal cancer (1 paper, 2018). "We selected data for lung (522 samples) and liver (422 samples) cancers in which the differences between ALDH2 and XRCC1 mRNA levels were pronounced and compared these data to oesophageal cancer (186 samples) in which XRCC1 and ALDH2 mRNA levels were very close." (PMID 30088263, 2018).
orchitis (1 paper, 2021). Inflammation of one or both testes due to viral or bacterial infections. "On the other hand, Klf2, Klf4, Nfe2l2/Nrf2, Id1, Id2, Rad21, Xrcc1, and Cycs were found to be negatively correlated with androgen synthesis during orchitis." (PMID 35111154, 2021).
prostate tumors (1 paper, 2022). "Using tissue microarrays, we found that prostate tumors from African American patients have more uracil and pyrimidine damage, elevated UNG levels, and reduced XRCC1 levels than European American tumors, which may indicate defects in the base excision repair pathway." (PMID 35205762, 2022).
pulmonary fibrosis (1 paper, 2022). Chronic progressive interstitial lung disorder characterized by the replacement of the lung tissue by connective tissue, leading to progressive dyspnea, respiratory failure, or right heart failure. "In this part, we summarize the reported scaffolding proteins linked to pulmonary fibrosis, XRCC1 and PARP-1." (PMID 36421478, 2022). "Currently, researchers are interested in the involvement of XRCC1 in pulmonary fibrosis after the use of chemotherapy drugs." (PMID 36421478, 2022). "Given that little is known about the mechanism of XRCC1 in pulmonary fibrosis, its clinical therapeutic potential needs to be further verified." (PMID 36421478, 2022).
skin toxicity (1 paper, 2013). "The XRCC1 399Arg/Gln was associated with high risk of grade 3 skin toxicity, OR = 2.65 (95% CI: 1.04–6.73), compared to the wild-type." (PMID 23375119, 2013). "Compared with XRCC1 194 Arg/Arg (wild-type), the XRCC1 194Arg/Trp was associated with lower incidence of grade 3 acute skin toxicity." (PMID 23375119, 2013).
testicular cancer (1 paper, 2022). A primary or metastatic malignant neoplasm that affects the testis. "No studies were found about these specific variants in testis or these genes in testicular cancer, but the role of IL1A, NFKB1 and XRCC1 have been reported in Sertoli cells and other essential factors for spermatogenesis." (PMID 35678683, 2022).
thymoma (1 paper, 2024). A neoplasm arising from the epithelial cells of the thymus. "Meanwhile, high expression of the XRCC1 gene was linked to better DFS in GBM (n=160, P=0.012) and thymoma (THYM) (n=118, P=0.019)." (PMID 38217545, 2024).
transient cerebral ischemia (1 paper, 2006). "Studies of transient cerebral ischemia in animal models suggest that an early decrease of XRCC1 protein levels and failure of the DNA repair mechanisms could contribute to DNA fragmentation." (PMID 17087834, 2006).
uterine carcinosarcoma (1 paper, 2024). A usually aggressive malignant neoplasm arising from the uterine corpus and less often the cervix. "Among these, the highest frequency of alterations in XRCC1 (>6%) was observed in patients with uterine carcinosarcoma (UCS), where “Amplification” was the predominant type of alteration." (PMID 38217545, 2024).
Uterine leiomyoma (1 paper, 2015). The presence of a leiomyoma of the uterus. "Haplotypes frequency of XRCC1 Arg399Gln and Arg194Trppolymorphisms in uterine leiomyoma women and control group." (PMID 26692154, 2015).
cancer (183 papers, 2002 to 2025). A tumor composed of atypical neoplastic, often pleomorphic cells that invade other tissues. "DNA damage plays an important role in cancer development, and the proteins encoded by XRCC1 and ERCC2 are important components of the DNA repair system." (PMID 39699591, 2025). "A detailed analysis was carried out by determining the correlation between the polymorphism of the XRCC1 Arg399Gln gene and age, sex, nicotinism, place of residence, and type of cancer or its stage." (PMID 40650316, 2025). "The study proved that the polymorphism of the XRCC1 gene is characterized by a statistically significant relationship with the onset of cancer." (PMID 40650316, 2025). "Results indicate the potential of the proposed team model to predict cancer risk based on XRCC1 SNP data." (PMID 40650316, 2025). "Polymorphism rs25487 of XRCC1 is associated with the risk of developing various types of cancer, including breast, lung, pancreatic, and nasopharyngeal cancers." (PMID 39699591, 2025). "Low XRCC1 mRNA and protein levels in cancer cells are associated with increased cancer risk, poorer survival, increased tumor aggressiveness, and resistance to some therapies." (PMID 40271221, 2025). "Several studies have shown the effectiveness of exploiting XRCC1 deficiency to enhance the therapeutic effects of DNA damaging cancer therapies, considering its important role in DNA repair." (PMID 40271221, 2025). "We conducted a comprehensive investigation into the potential of XRCC1 as a valuable diagnostic and prognostic indicator in diverse cancer types." (PMID 38217545, 2024). "Polymorphisms in the XRCC1 gene have been linked to various cancers due to this reduced DNA repair ability." (PMID 38337709, 2024). "In summary, our findings indicate that XRCC1 gene expression levels are predominantly associated with poor survival prognosis in various cancer types." (PMID 38217545, 2024). "Another important finding of this study is that XRCC1-associated infiltration of various immune cells correlates with cancer prognosis." (PMID 38217545, 2024). "The gene expression level of XRCC1 was strongly associated with TMB status across multiple cancer types, which on the other hand, supports the previous conclusions about XRCC1 and immune checkpoints." (PMID 38217545, 2024). "Epigenetic analysis revealed associations between XRCC1 expression and DNA methylation patterns in 10 cancer types, as well as enhanced phosphorylation." (PMID 38217545, 2024). "This suggests that XRCC1 is also associated with phosphorylation in the development of various types of cancer." (PMID 38217545, 2024). "Future investigations ought to concentrate on unraveling the mechanism underlying XRCC1's involvement in various cancer types, particularly in immunomodulation." (PMID 38217545, 2024). "Accordingly, we observed selective toxicity of Mirin in XRCC1 deficient cancer cells with an IC50 of 20 μM." (PMID 35853939, 2022). "SNV in the coding sequences of XRCC1 was shown to potentially associate with modulated DNA repair capacity, making it a risk factor to occurrence of various cancers, especially hematopoietic diseases." (PMID 35164849, 2022). "BER factors, including PARP1, POL β, and XRCC1, are frequently dysregulated in cancers and associated with poor survival outcomes." (PMID 35457130, 2022). "XRCC1 cancer-associated variants P161L, R194W, R280H, and Y576S showed almost same polβ interaction affinity with the wild-type protein as the KD values were in the range of 7 to 10 nM." (PMID 34339737, 2021). "We then examined DNA-binding affinities of XRCC1 wild-type and cancer-associated variants P161L, R194W, R280H, R399Q, and Y576S in real time using the BLI assay." (PMID 34339737, 2021). "A reduced BER capacity and cellular transformation have been reported in cells expressing XRCC1 cancer-associated variants in response to DNA damaging agents." (PMID 34339737, 2021).
cancer (continued). "Many studies have assessed the association between polymorphism in the XRCC1 gene and the risk of cancer in the female reproductive system, but the results have been inconclusive." (PMID 34918657, 2021). "While several single nucleotide polymorphisms, R399Q and R280H, have been correlated with cancer risk, variations in the gene and protein expression levels of XRCC1 are more commonly noted, particularly in ovarian, breast, and gastric cancers." (PMID 34067421, 2021). "Many studies have assessed the association between XRCC1 gene polymorphism and the risk of cancer in the female reproductive system, but the results have been inconclusive." (PMID 34918657, 2021). "For one nucleotide gap DNA-binding affinity of XRCC1 wild-type and the cancer-associated variants, P161L and Y576S, showed similar KD values that were in the range of 70 to 100 nM." (PMID 34339737, 2021). "Among these published studies, X-ray repair cross-complementing protein 1 (XRCC1) is one of the most studied genes and has been investigated for its possible association with cancer prognosis." (PMID 34094945, 2021). "Previous studies in other cancer types have reported the efficient targeting of PARP1 in XRCC1 deficient lines." (PMID 34067180, 2021). "For XRCC1 (rs25487) polymorphism, significantly increased cancer risk was seen in the recessive genetic model." (PMID 32711416, 2020). "Common variants of APE-1 (Asp/148 Glu) and XRCC1 (Arg194Trp, Arg280His, Arg399Gln) polymorphism, respectively, have been identified as potential cancer susceptibility loci." (PMID 32711433, 2020). "Currently, researches on XRCC1 mainly concentrate on the relationship between gene polymorphism and cancer susceptibility." (PMID 32426369, 2020). "This suggests that the interaction of Polβ with NQO1 is not regulated by the status of the Polβ complex with XRCC1 (bound to or free of XRCC1) but instead is impacted by the presence of the cancer mutation, T304I." (PMID 31287140, 2019). "GT type of ERCC1 and AA type of XRCC1 were associated with distal location of the cancer (p=0.018) and female gender (p=0.043), respectively." (PMID 31602266, 2019). "We have previously shown that loss of XRCC1 triggers metabolic changes resembling those found in many cancers." (PMID 30088263, 2018). "The associations between XRCC1 polymorphisms and the risk of cancer have been widely investigated, including lung cancer, gastric cancer, and colorectal cancer." (PMID 30362960, 2018). "Increasing epidemiological studies have been performed regarding the association between XRCC1 polymorphisms and cancer risk." (PMID 30362960, 2018). "Rs25487 on the XRCC1 gene (also known as Gln399Arg, and A allele encodes the Gln amino acid) was the polymorphism most studied in the risk of cancers." (PMID 29662639, 2018). "Evidence from 297 case-controlled studies found that the XRCC1 gene increases the overall risk for cancer." (PMID 29020930, 2017). "A high level of X-ray repair cross complementing group 1 (XRCC1) in cancer cells has been associated with the drug resistance occurrence." (PMID 29117108, 2017). "The X-ray repair cross-complementing group 1 (XRCC1) gene is a genetic variant that has been widely implicated in cancer susceptibility." (PMID 29020930, 2017). "Many studies have demonstrated that XRCC1 polymorphisms (i.e., rs1799782, Arg194Trp; rs25489, Arg280His; and rs25487, Arg399Gln) are associated with increased risk of cancer." (PMID 29156789, 2017). "Associations between XRCC1 SNPs and risk of female reproducitve system cancer are unclear, because the several molecular epidemiologic studies conducted so far have been inconclusive." (PMID 28415705, 2017). "Polymorphisms in XRCC1 have been demonstrated to associate with DNA adduct formation and an increased risk of cancer development." (PMID 27153553, 2016). "XRCC1 deficiency results in increasing frequencies of gene mutation and chromosomal aberrations, in turn increasing the risk of cancer." (PMID 27421136, 2016).